MFSD12 (major facilitator superfamily domain containing 12)
Diseases named in the same sentence as MFSD12 in open-access papers (continued):
Sharing a sentence is not in itself a finding about the gene and the disease.
tumor (8 papers, 2009 to 2025). "Further analyses revealed significant associations between MFSD12 expression and immune infiltration, immune checkpoint molecules, tumor mutation burden, and microsatellite instability in LIHC." (PMID 41194934, 2025). "This association was potentially attributed to MFSD12’s dual roles: promoting tumor cell proliferation, migration, and metastasis while critically modulating the tumor immune microenvironment, particularly through interaction with the HAVCR2/LGALS9 immune checkpoint axis." (PMID 41194934, 2025). "This established MFSD12 as a conserved regulator of tumor-associated immunity." (PMID 41194934, 2025). "In LIHC, the expression patterns of MFSD12 were significantly associated with clinical characteristics, whereas tumor-infiltrating lymphocytes serve as independent predictors of key clinical parameters, including tumor stage, grade, and lymph node status." (PMID 41194934, 2025). "To enhance our understanding of the anatomical distribution of MFSD12-expressing cells, we mapped the identified clusters to their respective tissue origins, including the tumor core, tumor edge, adjacent normal tissue, and blood." (PMID 41194934, 2025). "Analysis of tumor samples from the TCGA-LIHC cohort revealed significantly elevated MFSD12 expression compared to adjacent normal tissues (P < 0.001)." (PMID 41194934, 2025). "The HPA database and immunohistochemical analysis also revealed significantly higher MFSD12 expression in LIHC tissues compared to adjacent non-tumor tissues." (PMID 41194934, 2025). "Our findings revealed a total of 35 CpG methylation sites within the GCN1 region, with significantly reduced MFSD12 methylation levels observed in tumor tissue samples compared to normal tissues." (PMID 41194934, 2025). "We observed that increased expression of MFSD12 promoted tumor growth while creating an immune-evasive microenvironment by affecting immune cell recruitment and the production of immunosuppressive factors." (PMID 41194934, 2025). "The modular architecture of these interactions provides mechanistic insights into MFSD12-mediated tumor progression, likely through coordinated regulation of nutrient homeostasis and cellular stress resilience." (PMID 41194934, 2025). "miR-4732-3p functioned as a tumor suppressor in NSCLC by targeting 3'UTR of MFSD12, thereby inhibiting AKT/p21 signaling pathway to induce cell cycle arrest in G2/M phase." (PMID 38654325, 2024). "Herein, we elucidated the role of MFSD12 in promoting tumor growth, wherein its overexpression partially mitigated the suppressive effects of miR-4732-3p on NSCLC cells." (PMID 38654325, 2024). "In conclusion, miR-4732-3p suppresses NSCLC cell proliferation and tumor growth by modulating the MFSD12/AKT/p21 signaling pathway and inducing G2/M arrest." (PMID 38654325, 2024). "Then, the tumor samples were divided into two groups according to the expression of MFSD12, resulting in 98 patients with high expression and 99 patients with low expression." (PMID 30385854, 2019). "Its function as a cysteine transporter implies that MFSD12 may influence tumor development and metastasis by affecting cellular redox states and metabolic pathways." (PMID 41194934, 2025). "Furthermore, single-cell RNA sequencing revealed that MFSD12 was predominantly expressed in tumor cells and innate lymphoid cells (ILCs) within the tumor microenvironment." (PMID 41194934, 2025). "MFSD12 may promote tumor growth and metastasis by influencing metabolic and signaling pathways in cancer cells." (PMID 41194934, 2025). "Additionally, IHC analysis was performed to assess MFSD12 expression in 19 pairs of LIHC tumor tissues and their corresponding adjacent normal tissues." (PMID 41194934, 2025). "This progressive loss of methylation with advancing disease stage further underscores the dynamic nature of MFSD12 epigenetic regulation during LIHC progression and suggests that demethylation may be associated with more aggressive tumor behavior." (PMID 41194934, 2025).
tumor (continued). "The MFSD12-T254A mutant prevents tumor growth and MFSD12 function." (PMID 38903991, 2024). "Furthermore, we investigated MFSD12’s influence on the tumor immune microenvironment in LIHC." (PMID 41194934, 2025). "Therefore, MFSD12 may be an effective target to inhibit tumor development, block metastasis, and expand the therapeutic effect." (PMID 38903991, 2024). "In addition, previous studies have shown that expression of MFSD12, a novel suppressor gene in lung cancer, and its protein, can control cell cycle distribution, matrix attachment and cell motility, thereby regulating tumor growth and development." (PMID 35747825, 2022). "Subsequent to immunohistochemical analysis, it was determined that MFSD12 protein levels, as quantified by the integrated optical density (IOD) value, were significantly elevated in LIHC tissues compared to adjacent non-tumor tissues (P < 0.05)." (PMID 41194934, 2025). "This study aims to fill this gap by investigating the role of MFSD12 in LIHC progression and its interactions with the tumor immune microenvironment, ultimately identifying MFSD12 as a novel biomarker and potential therapeutic target." (PMID 41194934, 2025). "Our findings indicated that cells with high MFSD12 expression were predominantly localized within the tumor core and edge, while exhibiting a sparse distribution in normal tissues and blood." (PMID 41194934, 2025). "The findings supported the hypothesis that MFSD12 might enhance the infiltration and activity of CD8+ T cells and macrophages, thereby contributing to its role in the tumor microenvironment." (PMID 41194934, 2025). "Furthermore, we detected the mRNA expression level of these hub genes in our frozen tissues and found that FAM174B, MAD1L1, MFSD12, SLC45A2, and TBC1D16 were significantly upregulated in freshly frozen tumor tissues." (PMID 30385854, 2019). "Conversely, the negative correlation suggested that MFSD12 might lead to a diminished presence of cytotoxic and inflammatory cells within the tumor microenvironment, potentially facilitating tumor immune evasion and progression." (PMID 41194934, 2025).
cancer (6 papers, 2019 to 2025). A tumor composed of atypical neoplastic, often pleomorphic cells that invade other tissues. "MFSD12 plays an important role in moving compounds of biofilms and is associated with various cancers." (PMID 35250903, 2021). "Hallmark analysis indicated that MFSD12 upregulates interferon-γ response and inflammation, while downregulating Wnt/β-catenin signaling and androgen response, acting as both a promoter of immune pathways and a suppressor of cancer-related processes in the LIHC environment." (PMID 41194934, 2025). "MFSD12 demonstrated predominantly positive correlations across multiple cancer types, with distinct clusters indicating significant associations in specific cancers." (PMID 41194934, 2025). "Major Facilitator Superfamily Domain-containing 12 (MFSD12) has emerged as a critical transmembrane protein with increasingly recognized roles in various cancers." (PMID 41194934, 2025). "Our research found that MFSD12 mRNA expression was significantly higher in most cancer tissues compared to normal ones." (PMID 41194934, 2025). "The analysis demonstrated that MFSD12 mRNA expression was significantly elevated in the majority of cancer tissues relative to normal tissues." (PMID 41194934, 2025). "Through the application of R and various online analytical tools, our study demonstrated that MFSD12 expression levels were significantly higher in LIHC compared to other cancer types within the TCGA pan-cancer dataset." (PMID 41194934, 2025). "Next, we examined MFSD12 expression across 33 cancer types and its impact on 24 immune cell types, revealing distinct immunomodulatory patterns." (PMID 41194934, 2025). "This relationship highlighted the intricate interaction between MFSD12 and the immune system, which was essential for understanding its role in cancer biology and its potential therapeutic implications." (PMID 41194934, 2025). "A comparative analysis of MFSD12 differential expression between malignant and normal tissues was conducted across all cancer types." (PMID 41194934, 2025). "Functional analysis has shown that MFSD12 can be considered an effective target for the treatment of cancer." (PMID 38903991, 2024). "MFSD12’s role in cancer has garnered significant attention in recent years." (PMID 41194934, 2025). "In LIHC, the upregulation of MFSD12 might disrupt the normal regulation of the cell cycle, allowing cancer cells to divide more rapidly and evade apoptosis." (PMID 41194934, 2025). "Furthermore, we analyzed DNA methylation levels at specific CpG sites within the MFSD12 gene across various stages of cancer (Stage I to Stage IV)." (PMID 41194934, 2025). "Given the established oncogenic roles of MFSD12 in various cancer types, we hypothesized that it might similarly contribute to the progression of LIHC." (PMID 41194934, 2025). "The level of MFSD12 mRNA in different cancers was analyzed with GEPIA." (PMID 30385854, 2019). "Interestingly, both MFSD12 and SLC45A2 belong to the major facilitator superfamily, which plays important roles in moving compounds across biological membranes and is associated with a variety of cancers." (PMID 30385854, 2019). "The persistent occurrence of asterisks underscored the universal role of MFSD12 in macrophage recruitment, as evidenced by its positive association in 31 out of 33 cancer types, and in the suppression of Th17 cells, with a negative correlation observed in 29 out of 33 cancers." (PMID 41194934, 2025). "In addition to its involvement in the regulation of skin pigmentation, in recent years, more and more studies have shown that MFSD12 affects the progression of various diseases such as LSD and cancer by participating in lysosomal cysteine transport." (PMID 38903991, 2024).
cancer (continued). "In this experiment, the expression of MFSD12 and NUPR1 mRNA in the L. acidophilus KLDS1.0901 treatment group was lower than that of nontreated cells, indicating that low MFSD12 and NUPR1 are related to inhibiting cancer cell proliferation and promoting apoptosis." (PMID 35250903, 2021).
MFSD12 also shares sentences with these, for which no sentence is quoted: asthma (1 paper); lung squamous cell carcinoma (1); thyroid carcinoma (1).